FOXC2 (forkhead box C2)
Diseases named in the same sentence as FOXC2 in open-access papers (continued):
Sharing a sentence is not in itself a finding about the gene and the disease.
cancer (continued). "FOXC2, a known oncogene in several types of cancer, induces WNT4 in myoblast cell lines." (PMID 34298659, 2021). "Forkhead Box Protein C2 (FOXC2) promotes occurrence and development of various malignant tumors." (PMID 32222147, 2020). "Importantly, our differential gene expression analyses not only offer potential molecular explanations for well-established FOXC2-driven hallmarks of cancer progression but also suggest novel tumor-promoting functions for this transcription factor." (PMID 32175283, 2020). "Abnormal FOXC2 expression was found in tumorigenesis and malignant tumor development." (PMID 33505426, 2020). "In agreement, FOXF2 has shown to negatively regulate FOXC2-mediated cancer and EMT phenotypes." (PMID 32372224, 2020). "FOXC2 is widely accepted as an oncogene via interacting with cadherin family, protein kinases and other molecules to promote cell proliferation and metastasis in cancers." (PMID 32249539, 2020). "Our data now highlight the potential for FOXC2 to modify additional metabolic pathways in cancer cells, suggesting that this transcription factor may contribute to a variety of metabolic adaptations over the course of tumor progression." (PMID 32175283, 2020). "Forkhead box C2 (FOXC2) is a crucial factor involving in various cancers." (PMID 32508532, 2020). "In 199 Gleason score 7 carcinomas, 120 of 198 (61%) showed strong expression of FOXC2." (PMID 31464093, 2019). "They focused on AKT-mediated MMP-2 and MMP-9 to explain FOXC2-related cancer aggressiveness." (PMID 29801468, 2018). "Most of the studies chosen in our meta-analysis suggested that FOXC2 expression and cancer were associated, but none of them reported the relative risk between tumor stage and FOXC2 levels." (PMID 30279969, 2018). "Many studies have reported that FOXC2 is related to chemotherapeutic resistance in several cancers." (PMID 29801468, 2018). "It would be interesting to know if FOXC2 is also involved in this cancer circuit." (PMID 29487724, 2018). "FOXC2 has been reported to be an important EMT inducer via TGF-β signaling in several cancers." (PMID 29801468, 2018). "FOXC2 may also be involved in the lipid alterations of cancer via kinases in lipid metabolism, which represents an interesting research direction." (PMID 30360388, 2018). "Moreover, FOXC2 is also an important downstream player of PLK1 in cancer cells with stem cell properties." (PMID 27064522, 2016). "Targeting the COX-2/EP1/PKC/MAPK/E2F-1/FoxC2/β1-integrin pathway might represent a new therapeutic strategy for the prevention and treatment of this cancer." (PMID 27654511, 2016). "Finally, recent studies show that FOXC2 overexpression is involved in cancer progression, inducing epithelial mensenchymal transition (EMT)." (PMID 27276711, 2016). "Additionally, FOXC2 is known to induce cell proliferation and angiogenesis, which gives cancer cells stem cell-like properties." (PMID 27283491, 2016). "Furthermore, the role of Prox1 and FOXC2 in cancer cell growth and invasion was evaluated in cultured OSCC cells." (PMID 24647631, 2014). "FOXC2 protein may be transported outside the nucleus in certain types of cancers, and further studies will be needed to delineate the localization of FOXC2 in various cancers." (PMID 24647631, 2014). "Collectively, these observations suggest that FoxC2 is essential for tumor angiogenesis and disease progression and that FoxC2 may be a viable target for cancer therapy." (PMID 22174714, 2012). "The FoxC2 transcription factor is a newly recognized regulator of tumor angiogenesis and metastasis, and this paper summarizes what is currently known about the role of FoxC2 in cancer." (PMID 22174714, 2012). "The contribution of FoxC2 to lymphangiogenesis in pathological conditions such as cancer remains unknown." (PMID 22174714, 2012).
cancer (continued). "In addition, both FOXC2 and β-catenin hallmark gene sets are correlated with the downregulation of MYC targets, DNA repair, and oxidative phosphorylation, which are known characteristics of cancer progression." (PMID 40227590, 2025). "FOXC2 (Forkhead Box C2) is a transcription factor that is potentially involved in vascular formation during development and may promote neoangiogenesis through its role in developing vascular and lymphatic systems, mostly studied in cancerous tumors." (PMID 39698202, 2024). "Additionally, chronic or long-term AN treatment in cancer or oral epithelial cells promotes mesenchymal trans-differentiation, with the induction of multiple EMT-associated transcription factors; Slug, Twist, ZEB1, Snail, Grp78 and forkhead box C2 (FOXC2)." (PMID 36961055, 2023). "Thus, it is likely that FOXC2 is involved in VM in cancers other than HGSOC." (PMID 36230774, 2022). "Thus, we present a novel mechanism by which FOXC2 might contribute to cancer aggressiveness and poor patient survival." (PMID 36230774, 2022). "To determine whether FOXC2 expression in our model system has similar effects to those previously observed in various human cancer cell lines, we evaluated the cells for changes in morphology and growth patterns on plastic, soft agar, and ultra-low attachment plates." (PMID 36230774, 2022). "Hence, cells that have undergone EMT can promote tumor growth and neovascularization either indirectly, by promoting endothelial transdifferentiation of carcinoma cells, or directly, by acquiring an endothelial phenotype, with FOXC2 playing key roles in these processes." (PMID 33889304, 2021). "In addition, more evidence establishes the emerging role of FOXC2 in the development of cancer." (PMID 33505426, 2020). "Since we found that inhibition of FOXC2 changes the metabolism of cancer cells by promoting mitochondrial activity, future work is warranted to test whether combination treatment strategies can be employed to take advantage of altered metabolic states in cells that have features of EMT." (PMID 31652551, 2019). "Hence, FOXC2 might be secreted by the carcinoma cells to induce an osteogenic metastatic niche in the bone marrow." (PMID 31464093, 2019). "Our results indicate that FOXC2 expression is significantly more common in later-stage (T3-T4) tumors than in early stage (T1-T2) tumors and, consequently, that FOXC2 may be a marker for the T-stage of cancer." (PMID 30279969, 2018). "Moreover, FOXC2 can induce the expression of cancer-related genes, including AKT, GSK3β, and Snail." (PMID 29801468, 2018). "Finally, it is also important to mention that FOXC2 can modulate the metabolism of cancer cells." (PMID 30360388, 2018). "These factors may functionally activate EMT-inducing transcription factors, such as Snail (SNAI1), Slug (SNAI2), zinc finger E-box binding homeobox 1 (ZEB1), Twist family BHLH Transcription Factor 1 (Twist), Goosecoid (GSC), and forkhead box protein C2 (FOXC2) in cancer cells." (PMID 27270649, 2016). "However, the detailed role and function of Prox1 and FOXC2 in cancer remains controversial." (PMID 24647631, 2014). "FOXC2, a transcription factor, was found to be related to cell proliferation and epithelial‐mesenchymal transition (EMT) in cancer cells." (PMID 40998421, 2025). "Together, our work here identifies the critical role of a β-catenin/FOXC2 signaling axis in EMT, suggesting targets for TNBC and other cancers with EMT-induced mesenchymal and stemness properties." (PMID 40227590, 2025). "Critically, inhibiting FOXC2 by knocking it down or by inhibiting key positive regulators of FOXC2 blocks EMT induction, stemness, and metastasis, demonstrating the significance of targeting this critical protein in cancer." (PMID 40227590, 2025). "The Wnt/β-catenin pathway activates cancer stem cell maintenance via promotion of EMT transcription factors such as Snail and FOXC2." (PMID 40764669, 2025).
cancer (continued). "This study provides the first comprehensive analysis of long non-coding RNA and cancer stem cell gene expression in metastatic breast cancer, revealing SNAIL and FOXC2 as significantly regulated genes with robust biomarker potential." (PMID 40781106, 2025). "This FOXC2-mediated regulation of HOTAIR promotes chromatin remodeling, enhancing cancer cell invasiveness." (PMID 40781106, 2025). "In contrast, the expressions of FOXC2 and FOXO3 mRNA were significantly downregulated in cancer tissues (P < .001, the difference was statistically significant)." (PMID 38608123, 2024). "Overexpression of FOXM1, FOXC2 and FOXP1 have been shown to be important in tumor development, drug resistance, metastasis and poor prognosis in a variety of cancer types." (PMID 37401400, 2023). "Concomitant overexpression of both FOXC2 and WNT4 has been observed in some cancers, including CRC, suggesting FOXC2-mediated induction of WNT4 in tumor cells as well." (PMID 34298659, 2021). "More importantly, FOXC2 contributes to the metastatic process via EMT activation in many cancer growths and developments involving cancers of the breast, prostate, and ovary." (PMID 34868979, 2021). "Downstream transcription factors such as SNAI1, SNAI2, zinc finger E-box binding homeobox 1 and 2 (ZEB1 and ZEB2), TWIST1, Forkhead boxC2 (FOXC2), high mobility group A2 (HMGA2) and paired related homeobox 1 (PRX1) are subsequently activated in carcinoma." (PMID 31558913, 2019). "TGF-β would be the most responsible factor for induction of EMT by inducing EMT-inducing transcription factors in cancer cells, notably SNAIL, SLUG, ZEB1, TWIST, GOOSECOID, and FOXC2." (PMID 30453543, 2018). "In cancer, FOXC1 and FOXC2 are involved mainly in inducing angiogenesis, invasion and metastasis, invading growth suppressors, genome instability and mutation, and sustaining proliferative signaling." (PMID 30360388, 2018). "Both FOXC1 and FOXC2 have essential roles in the EMT process, angiogenesis, and target cancer stem cells." (PMID 30360388, 2018). "The cancer pathway finder PCR array revealed 9 genes, including ACSL4, BIRC3,CA9, CCL2, FLT1, FOXC2, G6PD, IGFBP3 and SNAI2, with significantly altered expression in the siRNA-treated MCF-7 cells." (PMID 27478411, 2016). "FOXC2 is a gene involved in epithelial to mesenchymal transition (EMT), a biological process acquired by cancer cells during cancer progression." (PMID 27634875, 2016). "FOXC2 is also one of the key players in the epithelial-to-mesenchymal transition (EMT) and EMT inducers, such as TGF-β, stimulate FOXC2 expression in cancer cells." (PMID 24647631, 2014). "While both proteins are independently associated with an increase of EMT, stemness, and metastasis in cancers, the FOXC2/β-catenin signaling interplay has not been extensively characterized in cancer stemness and mesenchymal traits." (PMID 40227590, 2025). "FOXC1 and FOXC2, some FOX subfamilies, appear to play a new role in cancer progression." (PMID 35178357, 2021). "Within the group of castration resistant cancers, no convincing survival differences were observed for FOXC2, E‐cadherin, N‐cadherin or the EN‐switch." (PMID 31464093, 2019). "FOXC2, similar to FOXC1, also has a vital role in the carcinogenesis of various cancers." (PMID 30360388, 2018). "Collectively, these data suggest that overexpression of FOXC2 and CLIP4 likely increases cell migration, which correlates to the synchronous metastasis of early-stage RCCs, whereas RELN may aid cancer cell survival." (PMID 27283491, 2016). "Several studies confirmed that FOXC2 mRNA and protein expression are induced by EMT-inducing factors (Snail, Twist, Goosecoid, Slug, SIP1, and E12/E47), which was discovered in various types of cancers." (PMID 27283491, 2016).
cancer (continued). "The molecular mechanisms and signaling pathways that control EndMT have yet to be elucidated; however, CAFs can develop directly from cancer cells through the epithelial-to-mesenchymal transition (EMT), which is regulated by FoxC2 (as discussed in the next section)." (PMID 22174714, 2012). "Moreover, our epithelial-to-mesenchymal transition (EMT) analysis revealed a consistent inverse association between PEBP1/STK11 co-expression and EMT marker genes, including SNAI1, SNAI2, FOXC2, ZEB1, and FN1, across most cancer types examined, thus underscoring a uniform anti-EMT signature." (PMID 40806276, 2025). "Notably, FOXC2 has the capacity to modulate the general upkeep of tumor cells and is involved in lipid alteration via kinases in tumor cells, whereas the role of FOXC1 in cancer metabolism is still a topic of research." (PMID 37626655, 2023). "This is not unexpected considering that FOXC2 is a major determinant of vascular development and remodeling during embryonic development and in adult tissues and contributes to angiogenesis during cancer progression." (PMID 36230774, 2022). "FOXC2 is also well-known for its ability to promote EMT and tumor cell migration/invasion, and our findings suggest potential mechanisms by which these hallmarks of cancer progression might be regulated by FOXC2 as well." (PMID 32175283, 2020). "We are therefore eager to explore in our model how FOXC2's negative regulation of RIG-I and other IFN pathway genes might contribute to tumor immune evasion and various forms of resistance to clinically relevant cancer immunotherapies." (PMID 32175283, 2020). "In addition, FOXC2, SALL4, CSF1 and BMI1 mRNA levels were also increased in Hep3B-TFF3 cells, all of which have recently been suggested to be involved in promoting CSC-like characteristics in various cancer cells." (PMID 28445151, 2017). "Moreover, regulation of FOXC2 and CLIP4 expression, which could suppress cell migration and inhibit tumor metastasis, would provide future helpful anti-cancer strategies to improve the survival of patients with metastatic ccRCCs." (PMID 27283491, 2016). "The role of FOXC2 in the skin homeostasis and cancer development is not known." (PMID 25785582, 2015). "However, the mesenchymal genes that are transcriptionally controlled by FOXC2, and the post-translational modifications of FOXC2 that regulate its function as an EMT-inducing and cancer-associated TF have not been studied." (PMID 25216525, 2014). "Given the important role of transcription factor Forkhead box C2 (FOXC2) in maintaining stem cell-like features and mesenchymal phenotype, inhibition of FOXC2 expression and subsequent EMT inhibition could restore GLS2 expression as well as glutamine utilization in cancer cells undergoing EMT." (PMID 38017510, 2023). "Thus, FOXC2 may be an important regulator in cancer proliferation in not only HCC but also other cancers." (PMID 29801468, 2018). "Critically, the β-catenin/FOXC2 signaling network’s involvement in the EMT-induced gain of mesenchymal and stemness properties, which are essential components in cancer progression and metastasis, have not been characterized." (PMID 40227590, 2025). "Our study revealed increased expression of c-Myc together with high expression of the mesenchymal markers VIM (Vimentin), FN1 (Fibronectin), ZEB2 (SIP-1), FOXC2, SNAIL1 (Snail), SNAIL2 (Slug), and TWIST and the cancer stem-like cell marker CD44 in cells and tumors lacking MCPIP1 RNase activity." (PMID 39815326, 2025). "Additionally, in our prior work that established the role of FOXC2 in carcinoma progression through the induction of EMT, we did not see β-catenin levels significantly change as a result of FOXC2 expression, an observation supported in PDAC." (PMID 40227590, 2025).
tumor (101 papers, 2010 to 2026). "One possibility is that FOXC1/FOXC2 loss results in tumour dedifferentiation, producing a more aggressive and plastic tumour phenotype." (PMID 40683913, 2025). "While our data indicates that FOXC2 promotes loss of epithelial character in tumor cells, the extent to which it endows cells with mesenchymal character is less clear." (PMID 37499655, 2023). "Previous studies have associated expression levels of FOXC2 with clinical and pathological characteristics including tumor size, differentiation, metastasis, and stage." (PMID 36425886, 2022). "FOXC2, a gene known to be associated with tumor aggressiveness and synchronous metastasis in ccRCC, based on our previous studies, was found to be associated with aggressive characteristics of tumors in early-stage ccRCC, in the present study." (PMID 31963294, 2020). "Within the individual studies, the relative risk of FOXC2 expression tended to be greater in T3-T4 tumor samples than in T1-T2 tumor samples." (PMID 30279969, 2018). "The authors found that FOXC2 expression was associated with a higher tumor grade (p = 0.178), and that patients with high FOXC2 expression had poorer prognoses and survival." (PMID 30279969, 2018). "With regard to CRC, previous studies have shown that DANCR might act as an oncogenic long non-coding RNA affecting tumor progression and FOXC2 has been implicated as an oncogene promoting tumor invasion and metastasis." (PMID 41039543, 2025). "Second, despite the fact that FOXC2 overexpression was associated with patient age, tumor differentiation, lymph node metastasis and TNM stage, we were unable to evaluate the association between FOXC2 overexpression and other clinical and pathological characteristics due to insufficient data." (PMID 36425886, 2022). "FOXC2 has also been linked to angiogenesis—both in the context of normal development and tumor progression—through its ability to transcriptionally regulate genes encoding pro-angiogenic factors including OPN, VEGF-A, ITGB-3, HEY-2, PDGF-β, DLL-4, CXCR-4, and ANG-2." (PMID 33889304, 2021). "Moreover, heterozygous mutant (Foxc2+/−) mice show significantly decreased expression of Vegf and Mmp2, and the haplo-deficiency of Foxc2 results even in impaired formation of tumour blood vessels as well as reduced tumour growth." (PMID 33076927, 2020). "Together with our observations in vitro and in vivo, our findings suggest that ZNF750, a significantly mutated driver gene in ESCC, may regulate tumor angiogenesis via DANCR/miR-4707-3p/FOXC2 axis that works in a ceRNA manner." (PMID 32341351, 2020). "However, many data suggest that the up-regulation of Foxc2, or its transfection, leads to an increase of cellular mobility often linked with progression, invasion and angiogensis of tumor." (PMID 23815774, 2013). "Moreover, we observed that high FOXC2 in expression GC tissues was significantly associated with more aggressive tumor phenotypes and shorter overall survival of GC patients than in patients with lower FOXC2 expression, as confirmed using the Kaplan-Meier plotter database." (PMID 33869020, 2021). "Through integrated single-cell and spatial multi-omics profiling, we identified a FOXC2+ tumor subpopulation endowed with vasculogenic mimicry capability as pivotal effector cells driving metastasis." (PMID 41610310, 2026). "In orthotopic lung metastasis models, FOXC2+ tumor cells leveraged LAMA4 to reshape the pulmonary metastatic niche, thereby reinforcing distant metastatic dissemination." (PMID 41610310, 2026). "On the other hand, this analysis revealed that FOXC2 OE in M cells led to a closed chromatin state at the CDx2 locus, a tumour suppressor gene frequently deleted in colon CSCs." (PMID 40764669, 2025). "M2-polarized HMC3 microglia promoted tumor angiogenesis by releasing exosomal circKIF18A, and circKIF18A bound to its target gene FOXC2 that upregulated ITGB3, CXCR4, and DLL4 expressions and activated PI3K/AKT signaling." (PMID 39781357, 2025).